GNA11 (G protein subunit alpha 11)
Description:
Guanine nucleotide-binding proteins (G proteins) function as transducers downstream of G protein-coupled receptors (GPCRs) in numerous signaling cascades. The alpha chain contains the guanine nucleotide binding site and alternates between an active, GTP-bound state and an inactive, GDP-bound state. Signaling by an activated GPCR promotes GDP release and GTP binding. The alpha subunit has a low GTPase activity that converts bound GTP to GDP, thereby terminating the signal. Both GDP release and GTP hydrolysis are modulated by numerous regulatory proteins. Signaling is mediated via phospholipase C-beta-dependent inositol lipid hydrolysis for signal propagation: activates phospholipase C-beta: following GPCR activation, GNA11 activates PLC-beta (PLCB1, PLCB2, PLCB3 or PLCB4), leading to production of diacylglycerol (DAG) and inositol 1,4,5-trisphosphate (IP3). Transduces FFAR4 signaling in response to long-chain fatty acids (LCFAs). Together with GNAQ, required for heart development (By similarity). In the respiratory epithelium, transmits OXGR1-dependent signals that lead to downstream intracellular Ca(2+) release and mucocilliary clearance of airborne pathogens.
Synonyms: FBH; FBH2; FHH2; GNA-11; HG1K; HHC2; HYPOC2
Tractability: Small molecule: a structure with a bound ligand is known; a high-quality ligand is known. Antibody: UniProt places it where antibodies can reach, with high confidence; its Gene Ontology location is reachable by antibodies, with high confidence. PROTAC: ubiquitination databases record sites on it; its protein half-life has been measured; a small molecule that binds it is known.
Target class: Other membrane protein
Gene: Protein-coding gene on chromosome 19 (3,094,362 to 3,123,999, forward strand). Ensembl gene ENSG00000088256.
Subcellular location: Cell membrane; Cytoplasm
Pathways (Reactome):
Hemostasis: ADP signalling through P2Y purinoceptor 1; Thrombin signalling through proteinase activated receptors (PARs); Thromboxane signalling through TP receptor
Signal Transduction: G alpha (q) signalling events; G-protein activation; PLC beta mediated events
Cellular responses to stimuli: High laminar flow shear stress activates signaling by PIEZO1 and PECAM1:CDH5:KDR in endothelial cells; Turbulent (oscillatory, disturbed) flow shear stress activates signaling by PIEZO1 and integrins in endothelial cells
Metabolism: Acetylcholine regulates insulin secretion; Fatty Acids bound to GPR40 (FFAR1) regulate insulin secretion
Metabolism of proteins: Cooperation of PDCL (PhLP1) and TRiC/CCT in G-protein beta folding
Gene Ontology:
Molecular function: G protein activity; protein binding; G protein-coupled receptor binding; G-protein beta/gamma-subunit complex binding; GTP binding; GTPase activity; guanyl nucleotide binding
Biological process: phospholipase C-activating G protein-coupled receptor signaling pathway; action potential; adenylate cyclase-modulating G protein-coupled receptor signaling pathway; entrainment of circadian clock; G protein-coupled acetylcholine receptor signaling pathway; phospholipase C-activating dopamine receptor signaling pathway; phototransduction, visible light; signal transduction; cranial skeletal system development; endothelin receptor signaling pathway; G protein-coupled receptor signaling pathway; phospholipase C-activating G protein-coupled acetylcholine receptor signaling pathway; regulation of blood pressure
Cellular component: cytoplasm; cytoplasmic side of plasma membrane; extracellular exosome; lysosomal membrane; plasma membrane; photoreceptor outer segment; synapse
Genetic constraint (gnomAD): Loss-of-function variants: 8 observed, 37.94 expected, observed/expected ratio (o/e) 0.21, 90% interval 0.12 to 0.38. The upper end of that interval is the gene's LOEUF score, 0.38, which puts it in group 1 of 6, group 1 being the genes least tolerant of losing a copy. Missense variants: 268 observed, 507.26 expected, observed/expected ratio (o/e) 0.53, 90% interval 0.48 to 0.58. Synonymous variants: 211 observed, 217.5 expected, observed/expected ratio (o/e) 0.97, 90% interval 0.87 to 1.09.
Cancer hallmarks: proliferative signalling (promotes)
Homologues: Orthologues: chimpanzee GNA11 (100% identical), macaque GNA11 (99% identical), pig GNA11 (99% identical), dog GNA11 (98% identical), mouse Gna11 (98% identical), rat Gna11 (97% identical), tropical clawed frog gna11 (92% identical), guinea pig GNA11 (87% identical), Drosophila melanogaster CG30054 (66% identical), Drosophila melanogaster CG17760 (62% identical), zebrafish gna15.1 (58% identical), zebrafish gna15.2 (52% identical), and 14 more. Paralogues in human: GNAQ (90% identical), GNA14 (81% identical), GNA15 (57% identical), GNAI1 (52% identical), GNAI3 (51% identical), GNAI2 (50% identical), GNAT2 (50% identical), GNAO1 (49% identical), GNAT1 (49% identical), GNAT3 (49% identical), GNA13 (47% identical), GNAZ (46% identical), and 3 more.
Diseases named in the same sentence as GNA11 in open-access papers:
GNA11 is named in the same sentence as 154 diseases in open-access papers, as found by Europe PMC text mining. Sharing a sentence is not in itself a finding about the gene and the disease. The quoted sentences say what the papers report.
uveal melanoma (178 papers, 2011 to 2026). A melanoma derived from melanocytes of the uveal tract. "The second most cited paper, with 53 citations, is authored by van Raamsdonk CD, published in 2010 in The New England Journal of Medicine under the title Mutations in GNA11 in Uveal Melanoma." (PMID 40607060, 2025). "The MAPK cascade, initiated by common activating mutations in GNAQ and GNA11, is the main oncogenic pathway driving uveal melanoma." (PMID 41154654, 2025). "Molecularly, mutually exclusive gain-of-function mutations in GNAQ and GNA11 genes, which encode for Gα subunits of G-proteins, are found in 85–95% of uveal melanomas and drive tumor initiation." (PMID 41362626, 2025). "Other disorders such as familial hypocalciuric hypercalcemia type 2 (FHH2) and autosomal dominant hypocalcemia type 2 (ADH2) are associated with germline GNA11 variants, and uveal melanoma is associated with somatic GOF variants of GNA11 and GNAQ." (PMID 39743506, 2025). "Key findings include the potential therapeutic value of FTIs for NRAS-mutated melanoma and GNAQ/GNA11-mutated uveal melanoma by inhibiting INPP5A farnesylation." (PMID 39995872, 2025). "This study offers an in-depth analysis of the role of GNA11 mutations in uveal melanoma, emphasizing the connection between these mutations and disease prognosis as well as the tumor’s biological characteristics." (PMID 40607060, 2025). "GNA11 mutations occur in 40–45 % in uveal melanoma and is involved in constitutive activation of signalling pathways downstream of G-protein-coupled receptors." (PMID 40491523, 2025). "Mutant constitutively active (CA) G protein α-subunits encoded by GNAQ or GNA11 (CA-GNAQ/11) drive uveal melanoma (UM), occur in uncommon subtypes of other cancers, and cause Sturge–Weber syndrome and other capillary malformations." (PMID 40812428, 2025). "Protein kinase C (PKC) is activated downstream of gain-of-function GNAQ or GNA11 (GNAQ/GNA11) mutations in over 90% of uveal melanoma (UM)." (PMID 38418838, 2024). "Mutations in GNAQ and GNA11 are predominantly found in uveal melanoma, a type of melanoma originating in the eye." (PMID 39200315, 2024). "In a clinical study, patients treated with darovasertib demonstrated a 50% reduction in tumor size, highlighting the potential of targeting GNAQ and GNA11 mutations to develop effective treatments for uveal melanoma." (PMID 39200315, 2024). "Mutations in G-protein subunits, specifically GNAQ and GNA11, are prevalent in uveal melanoma, occurring in approximately 85% of cases in a mutually exclusive pattern." (PMID 39061150, 2024). "The majority of uveal melanomas have mutations in GNAQ or GNA11 leading to activation of the MAPK pathway." (PMID 38683104, 2024). "GNAQ/GNA11 mutations, commonly identified in uveal melanomas, represent a distinct genetic subgroup within melanoma." (PMID 38474231, 2024). "Greater than 80% of uveal melanomas have a mutation in GNAQ or GNA11 which lead to downstream signaling through the MAPK pathway." (PMID 38683104, 2024). "Activating mutations in GNAQ/GNA11 occur in over 90% of uveal melanomas (UMs), the most lethal melanoma subtype; however, targeting these oncogenes has proven challenging and inhibiting their downstream effectors show limited clinical efficacy." (PMID 38233483, 2024). "Spitz melanomas show tyrosine kinase or serine-threonine kinase fusions, and melanomas in blue nevi and uveal melanomas often contain GNA11 or GNAQ mutations." (PMID 38474231, 2024). "Manchado and colleagues combine CRISPR screening and transcriptomics to identify INPP5A as a dependency and therapeutic target in uveal melanoma driven by mutations in GNAQ/GNA11 and show that IP4 levels correlate with sensitivity to INPP5A loss." (PMID 38233483, 2024). "The distribution of GNAQ and GNA11 mutation signatures also provides further supporting molecular evidence for a light or UV exposure dependent mechanism in uveal melanoma." (PMID 35338357, 2023).
uveal melanoma (continued). "Mutation analysis of tumor tissue revealed BRAF V600E/K mutation in 16 (64%), NRAS mutation in 2 (8%) and GNAQ or GNA11 mutation in 4 (n = 2, 8%; uveal melanoma; n = 2, 8%, primary CNS melanoma) patients." (PMID 36997799, 2023). "Mutations in theGNAQ and GNA11 genes have been found to be associated with uveal melanoma, while they are rarely associated with mucosal melanoma." (PMID 37284406, 2023). "Activating mutations in the genes coding for G protein subunit alpha q (GNAQ) or G protein subunit alpha 11 (GNA11) are present in approximately 90% of uveal melanoma patients, and the GNA11 mutation rate is significantly dependent on PKC activity." (PMID 37576814, 2023). "They differ, for instance, in the oncogenic driver mutations, mainly alterations in MAPK signaling in cutaneous melanoma and alterations in GNAQ/GNA11 signaling or the BRCA1-associated protein BAP1 in uveal melanomas." (PMID 37577930, 2023). "GNAQ and GNA11 mutations are present in 55% and 50%, respectively, of primary uveal melanoma patients." (PMID 37576814, 2023). "The GNAQ and GNA11 genes are mutated in almost 80–90% of uveal melanomas in a mutually exclusive pattern." (PMID 35804836, 2022). "Mutations affecting Q209 in GNA11 were present in 32% of primary uveal melanomas and 57% of uveal melanoma metastases." (PMID 35975235, 2022). "Both GNAQ and GNA11 genes codify for α-subunits of G-coupled proteins and have been recognized as uveal melanoma driver mutations." (PMID 35409195, 2022). "Recent studies have found that GNA11 mutation was associated with uveal melanoma, the most prevalent primary intraocular malignancy in adults." (PMID 35877357, 2022). "Instead, activating mutations in GNAQ or GNA11 genes occur in 80–90% of uveal melanoma cases in a mutually exclusive pattern." (PMID 35409195, 2022). "Activating Gαq signalling mutations at mutually-exclusive hotspots in GNAQ and GNA11 (p.Q209 and p.R183) are found in a large majority of uveal melanomas." (PMID 33588787, 2021). "Over 90% of uveal melanomas harbor pathogenic variants of the GNAQ or GNA11 genes that activate survival pathways." (PMID 34533562, 2021). "It was reported that 80% uveal melanomas have GNAQ or GNA11 mutations, which were potential drivers of MAPK activation; and a randomized phase II trial of selumetinib, a selective MEK inhibitor, has shown prospective therapeutic effect for uveal melanomas." (PMID 34568004, 2021). "As mentioned, activating GNAQ and GNA11 mutations were first identified in cutaneous blue nevi and uveal melanoma." (PMID 34040639, 2021). "Identifying GNAQ or GNA11 mutations can be useful to diagnose uveal melanoma and differentiate it from other types of melanomas and melanoma of undefined origin." (PMID 34441278, 2021). "The mTOR pathway is one of the many survival pathways activated by pathogenic variants in the GNAQ or GNA11 genes, supporting the need for investigations into the efficacy of therapies for uveal melanoma containing mTOR inhibitors." (PMID 34533562, 2021). "Recent experimental studies have demonstrated an essential role for the Hippo-Yes-associated protein (YAP) pathway in GNAQ/GNA11-induced tumorigenesis in uveal melanoma (UM)." (PMID 32277165, 2020). "GNAQ and GNA11 mutations were amplified by real-time PCR in the circulating DNA from the plasma of 22 patients with uveal melanoma, and Q209 mutations were detected by ultradeep sequencing in 9 of these." (PMID 32532044, 2020). "GNA11 codes for guanine nucleotide-binding transducer of transmembrane signaling that is highly mutated in uveal melanoma." (PMID 33227964, 2020). "Apart from being found in the meninges (59%), in blue naevi (83%), and in a subset of cutaneous melanomas linked to chronic sun-induced damage (3–4%), GNAQ or GNA11 represent driver oncogenes in around 50% uveal melanoma." (PMID 32532044, 2020). "GNA11 encodes the G protein’s alpha subunit and is involved in causing various cancers, particularly uveal melanoma." (PMID 32225122, 2020).
uveal melanoma (continued). "Analysis of oncogene status showing positive GNAQ or GNA11 expression can be a valuable diagnostic tool to differentiate uveal melanoma from other types of melanoma and cancers." (PMID 32429485, 2020). "For example, several zebrafish models of uveal melanoma have shown that melanocyte-specific expression of driver mutations GNAQ/GNA11(Q209L) led to considerable changes in the melanocyte biology of the fish." (PMID 32532044, 2020). "Uveal melanoma has been thought to result from an initiating GNAQ/GNA11 mutation, followed by a secondary BSE event from mutations in the genes BAP1, SF3B1, and EIF1AX." (PMID 32429485, 2020). "Mutations in GNAQ (50%) and GNA11 (44%) are early events that promote cell proliferation, suggesting that activated G-protein signaling plays a crucial role in early uveal melanoma development." (PMID 31598164, 2019). "Mutations in NRAS only occur in 10–20% of mucosal melanomas, while mutations in GNAQ and GNA11 that are commonly detected in uveal melanoma, occur in approximately 9.5% of mucosal melanomas." (PMID 30847022, 2019). "In conclusion, this study found that somatic mutations in GNAQ and GNA11 occur frequently in uveal melanoma in Chinese people." (PMID 35693877, 2019). "Second, it appears to be genetically distinct from cutaneous melanoma, with driver mutations in GNAQ and GNA11 being most common in uveal melanoma, while Braf and Nras are the most common driver mutations in cutaneous melanoma." (PMID 31320995, 2019). "The predominant mutations present in uveal melanoma are in GNAQ or the mutually exclusive GNA11 gene, which are mutated in 90% of uveal melanomas." (PMID 31046743, 2019). "In this study, one-third (33.3%) of 63 Chinese primary uveal melanoma samples carried mutations in Q209 of GNAQ or GNA11, while the frequency was 76.6% in the Caucasian population." (PMID 35693877, 2019). "The high frequency of Q209 mutations and the large number of novel missense mutations found in this study suggest that somatic mutations in GNAQ and GNA11 are also frequent in uveal melanoma in Chinese people." (PMID 35693877, 2019). "Minor percentages of melanomas have activating mutations in the KIT gene, most common in mucosal melanomas derived from the genital regions or mutations in G Protein Subunit Alpha 11 (GNA11) or G Protein Subunit Alpha q (GNAQ) genes in uveal melanomas." (PMID 30884760, 2019). "The activation of the mitogen-activated protein kinase (MAPK) pathway has been suggested as the major downstream target when GNAQ and GNA11 (GNAQ/11) are mutated in uveal melanoma (UM)." (PMID 31173078, 2019). "The high mutation frequency of Q209 and the novel missense mutations detected in this study suggest that GNAQ and GNA11 are common targets for somatic mutations in Chinese uveal melanoma." (PMID 35693877, 2019). "Driver mutations in GNAQ and GNA11 were identified in two uveal melanomas, and a driver mutation in KIT was found in mucosal melanoma." (PMID 29991680, 2018). "GNAQ mutations have been found in thyroid cancer and GNAQ/GNA11 mutations are able to initiate human uveal melanoma." (PMID 29324665, 2018). "Based on the variant GNA11 Q209L identified in the uveal melanoma of patient 8 off-label treatment with sorafenib was decided by the tumor board." (PMID 30373609, 2018). "Point mutations in GNAQ and GNA11 have been identified in 80–90% of uveal melanomas and lead to activation of the MAPK/MEK/ERK pathway." (PMID 29326884, 2017). "GNAQ and GNA11 mutations have been identified in the plasma of uveal melanoma patients and are rare in other tumour types." (PMID 29061138, 2017). "Activating mutations in GNAQ and GNA11, which are commonly detected in uveal melanoma, have recently been reported to occur in 9.5% of mucosal melanomas, a finding not reported in previous studies." (PMID 28380455, 2017). "Another study carried out by the same investigators showed frequent mutations in uveal melanoma of the gene GNA11, encoding for a GNAQ paralogue." (PMID 29156643, 2017).